RABGAP1L (RAB GTPase activating protein 1 like)
Description:
GTP-hydrolysis activating protein (GAP) for small GTPase RAB22A, converting active RAB22A-GTP to the inactive form RAB22A-GDP. Plays a role in endocytosis and intracellular protein transport. Recruited by ANK2 to phosphatidylinositol 3-phosphate (PI3P)-positive early endosomes, where it inactivates RAB22A, and promotes polarized trafficking to the leading edge of the migrating cells. Part of the ANK2/RABGAP1L complex which is required for the polarized recycling of fibronectin receptor ITGA5 ITGB1 to the plasma membrane that enables continuous directional cell migration (By similarity).
Synonyms: HHL; KIAA0471; TBC1D18; FLJ38519
Tractability: PROTAC: ubiquitination databases record sites on it; its protein half-life has been measured.
Safety:
Unwanted effects reported when the protein is acted on. In parentheses: how it was acted on, where the effect was seen, and who reports it.
alcoholism (source: ClinPGx)
Gene: Protein-coding gene on chromosome 1 (174,159,410 to 174,995,308, forward strand). Ensembl gene ENSG00000152061.
Subcellular location: Cytoplasmic vesicle; Early endosome; Golgi apparatus
Gene Ontology:
Molecular function: GTPase activator activity; protein binding; small GTPase binding
Biological process: regulation of protein localization
Cellular component: early endosome; Golgi apparatus; nucleus; cytoplasmic vesicle; cytoplasm
Genetic constraint (gnomAD): Loss-of-function variants: 47 observed, 102.31 expected, observed/expected ratio (o/e) 0.46, 90% interval 0.36 to 0.59. The upper end of that interval is the gene's LOEUF score, 0.59, which puts it in group 2 of 6, group 1 being the genes least tolerant of losing a copy. Missense variants: 929 observed, 1,075.2 expected, observed/expected ratio (o/e) 0.86, 90% interval 0.82 to 0.91. Synonymous variants: 372 observed, 375.75 expected, observed/expected ratio (o/e) 0.99, 90% interval 0.91 to 1.08.
Homologues: Orthologues: pig RABGAP1L (97% identical), guinea pig RABGAP1L (95% identical), rat Rabgap1l (94% identical), chimpanzee RABGAP1L (77% identical), tropical clawed frog rabgap1l (76% identical), macaque RABGAP1L (76% identical), dog RABGAP1L (74% identical), rabbit RABGAP1L (73% identical), mouse Rabgap1l (72% identical), zebrafish rabgap1l (21% identical), zebrafish rabgap1l2 (15% identical). Paralogues in human: RABGAP1 (65% identical), TBC1D1 (15% identical), TBC1D4 (15% identical), TBC1D9B (15% identical), TBC1D8B (15% identical), TBC1D9 (14% identical), TBC1D8 (14% identical), TBC1D2B (13% identical), EVI5L (13% identical), TBC1D10B (13% identical), EVI5 (12% identical), TBC1D2 (12% identical), and 33 more.
Diseases named in the same sentence as RABGAP1L in open-access papers:
RABGAP1L is named in the same sentence as 15 diseases in open-access papers, as found by Europe PMC text mining. Sharing a sentence is not in itself a finding about the gene and the disease. The quoted sentences say what the papers report.
leukemia (2 papers, 2018 to 2021). A malignant (clonal) hematologic disorder, involving hematopoietic stem cells and characterized by the presence of primitive or atypical myeloid or lymphoid cells in the bone marrow and the blood. "It has been reported that the Rab GTPase activating protein 1-Like (Rabgap1l)-mediated tyrosine kinase signal transduction pathway plays a major role in the pathogenesis of leukemia." (PMID 30424520, 2018).
fibromyalgia (1 paper, 2025). A chronic disorder of unknown etiology characterized by pain, stiffness, and tenderness in the muscles of neck, shoulders, back, hips, arms, and legs. "RABGAP1L regulates RAB proteins, which direct intracellular trafficking, but has no clear link to fibromyalgia." (PMID 41001472, 2025).
lung carcinoma (1 paper, 2020). "At present, there is no known role for RABGAP1L in lung cancer." (PMID 32601340, 2020).
ovarian carcinoma (1 paper, 2025). A malignant neoplasm originating from the surface ovarian epithelium. "We found that the expression of BANF1, CDK2AP2, DDT, LRIG1, MRPL4, and S100A13 was upregulated in ovarian cancer samples, and the expression of EPS8, NUCB2, PAF1, PMP22, RABGAP1L, and USO1 was upregulated in normal samples." (PMID 41000388, 2025).
tumor (5 papers, 2016 to 2025). "RABGAP1L displayed predominant hypomethylation and was upregulated in primary tumor samples, with cfDNA methylation analysis confirming hypomethylation within intron 17 (748 bp)." (PMID 40943642, 2025). "Based on tumor stage features and the expression of the three identified candidate genes, RABGAP1L, MYH9, and DRD4, we developed logistic regression models for the prediction of CRC patient prognosis by ML." (PMID 36345155, 2023). "These clones harboured nonsynonymous mutations in genes that may be associated with tumour cell proliferation and invasion, such as RASGRF1 and RABGAP1L." (PMID 34507604, 2021). "Interestingly, Model 1 (the model of tumor stage and RABGAP1L) showed the highest performance of OS predictions (AUC = 0.69, F1 score = 0.26) compared with baseline (AUC = 0.66, F1 score = 0.24) and other models (average AUC = 0.64, F1 score = 0.242) in Chonnam‐COAD." (PMID 36345155, 2023). "For the prediction of Chonnam‐COAD DFS prognosis, Model 3 (tumor stage + DRD4) had the highest AUC (0.72 vs. 0.64 ± 0.02), whereas Model 7 (tumor stage + RABGAP1L + MYH9 + DRD4) had the highest F1 score (0.33 vs. 0.3 ± 0.015)." (PMID 36345155, 2023). "The analysis revealed that in the training set, the expression of BANF1, CDK2AP2, DDT, LRIG1, MRPL4, and S100A13 was significantly upregulated in tumor samples, and the expression of EPS8, NUCB2, PAF1, PMP22, RABGAP1L, and USO1 was higher in control samples (p < 0.05)." (PMID 41000388, 2025).
cancer (3 papers, 2016 to 2021). A tumor composed of atypical neoplastic, often pleomorphic cells that invade other tissues. "We reported that the CpG methylation status of CCDC150 and RABGAP1L could have prognostic values in HCC, which linked the functions of these two genes to cancer development." (PMID 35111672, 2021). "Both RabGAP1L and AAMDC were co-expressed on the plasma-membrane, in the cytoplasm, and/or in the nucleus of luminal cancer cells, as assessed by IF." (PMID 33772001, 2021).
infection (1 paper, 2026). The state of being infected such as from the introduction of a foreign agent such as serum, vaccine, antigenic substance or organism. "Despite inter-individual variability and cohort heterogeneity, our findings regarding four DMPs (IFI44L, MX1, DDX60, and RABGAP1L) and two DMRs (PARP9 and GNA12) replicate changes described both in the acute phase of infection and at long-term follow-up." (PMID 42288901, 2026).
RABGAP1L also shares sentences with these, for which no sentence is quoted: Alzheimer disease (1 paper); depression (1); duodenitis (1); gastritis (1); insomnia (1); microcephaly (1); psychiatric disorder (1); schizophrenia (1).